SNORD62B (small nucleolar RNA, C/D box 62B)
Synonyms: U62; U62B
Gene: Small nucleolar RNA gene on chromosome 9 (131,490,486 to 131,490,571, forward strand). Ensembl gene ENSG00000231587.
Gene Ontology:
Biological process: RNA processing
Cellular component: nucleolus
Homologues: Orthologues: macaque SNORD62 (100% identical), mouse Gm22192 (95% identical), pig SNORD62 (92% identical), dog SNORD62 (91% identical), guinea pig SNORD62 (78% identical), tropical clawed frog SNORD62 (78% identical), tropical clawed frog SNORD62 (71% identical), rabbit SNORD62 (60% identical). Paralogues in human: SNORD62A (100% identical), SNORD62 (85% identical).